TENT5D (terminal nucleotidyltransferase 5D)
Description:
Catalyzes the transfer of one adenosine molecule from an ATP to an mRNA poly(A) tail bearing a 3'-OH terminal group.
Synonyms: FAM46D; MGC26999; CT1.26; CT112
Tractability: No criterion of Open Targets' tractability assessment is met for any kind of drug.
Gene: Protein-coding gene on chromosome X (80,335,504 to 80,445,311, forward strand). Ensembl gene ENSG00000174016.
Gene Ontology:
Molecular function: poly(A) RNA polymerase activity; protein binding
Biological process: mRNA stabilization
Homologues: Orthologues: chimpanzee TENT5D (98% identical), macaque TENT5D (94% identical), pig TENT5D (83% identical), dog TENT5D (82% identical), rat Tent5d (78% identical), mouse Tent5d (77% identical), rabbit TENT5D (71% identical), tropical clawed frog tent5d (69% identical), zebrafish tent5d (65% identical), Drosophila melanogaster CG46385 (52% identical), Caenorhabditis elegans tent-5 (41% identical), Caenorhabditis elegans T23F11.6 (12% identical), and 4 more. Paralogues in human: TENT5A (60% identical), TENT5C (58% identical), TENT5B (50% identical).
Diseases named in the same sentence as TENT5D in open-access papers:
TENT5D is named in the same sentence as 12 diseases in open-access papers, as found by Europe PMC text mining. Sharing a sentence is not in itself a finding about the gene and the disease. The quoted sentences say what the papers report.
male infertility (2 papers, 2018 to 2024). The inability of the male to effect fertilization of an ovum after a specified period of unprotected intercourse. "Notably, disruption of TENT5D leads to oligoasthenoteratozoospermia and male infertility in humans." (PMID 38909026, 2024).
autism (1 paper, 2018). Persistent deficits in social interaction and communication and interaction as well as a markedly restricted repertoire of activity and interest as well as repetitive patterns of behavior. "TENT5D dysfunction might also be related to autism as TENT5D is overexpressed in the cerebral cortex of mice with autism-like behaviours." (PMID 30397099, 2018).
Infertility (1 paper, 2025). "For instance, the defect of TENT5D causes infertility in humans." (PMID 39794363, 2025).
leukemia (1 paper, 2026). A malignant (clonal) hematologic disorder, involving hematopoietic stem cells and characterized by the presence of primitive or atypical myeloid or lymphoid cells in the bone marrow and the blood. "Furthermore, our results also suggest that in leukemia cells, TENT4A, TENT5A, TENT5B, TENT5C, TENT5D, and TUT1 may mediate the non-templated nucleotide additions to the 3'ends of miRNAs." (PMID 42038404, 2026).
testis cancer (1 paper, 2021). "It has been proposed to be a testis cancer antigen, in which the TENT5D gene has a restricted expression pattern in the normal testis but is aberrantly expressed in testicular cancer." (PMID 33145994, 2021).
TENT5D also shares sentences with these, for which no sentence is quoted: cancer (2 papers); autism spectrum disorder (1); gastric cancer (1); non-small cell lung carcinoma (1); oligoasthenoteratozoospermia (1); prostate carcinoma (1); tumor (1).